RAB3B (RAB3B, member RAS oncogene family)
Diseases named in the same sentence as RAB3B in open-access papers (continued):
Sharing a sentence is not in itself a finding about the gene and the disease.
tumor (14 papers, 2014 to 2025). "RAB3B was positively associated with tumor staging, and miR-3158-5p was negatively associated with tumor staging." (PMID 36613779, 2022). "A total of 10,953 patients from the TCGA database were analyzed using the cBioPortal platform to determine whether the RAB3B gene was mutated in tumor tissues." (PMID 38688977, 2024). "Thus, RAB3B can be utilized as an auxiliary diagnostic marker for early tumor detection and a prognostic biomarker for various tumor types." (PMID 38688977, 2024). "Interestingly, it has been found that eccDNA amplification in genes like EGFR, c-MYC, and RAB3B, which are associated with autophagy, can intensify the "stemness" of tumor cells." (PMID 39534571, 2023). "In addition, overexpression of RAB3B has been associated with the prognosis, clinicopathological features, and the proliferation ability of tumor cells." (PMID 33330502, 2020). "Furthermore, RAB3B showed potential associations with tumor heterogeneity and immunity." (PMID 38688977, 2024). "The findings indicated notable variations in the levels of RAB3B expression among three tumor types, namely DLBC, PAAD, and READ." (PMID 38688977, 2024). "Further investigation revealed a significant correlation between CD276 and RAB3B in 22 tumor types, highlighting the need for further mechanistic studies." (PMID 38688977, 2024). "The findings indicated that RAB3B exhibits a specific level of accuracy in diagnosing tumor samples in 11 datasets (AUC > 0.7) and normal samples in five datasets (AUC > 0.7)." (PMID 38688977, 2024). "Through the analysis of the gene expression profiles of 33 tumors in the TCGA database, it was discovered that the expression levels of RAB3B exhibited notable disparities among different tumor samples and normal samples." (PMID 38688977, 2024). "In contrast, the levels of RAB3B protein expression were notably elevated in tumor samples of BRCA, LIHC, LUAD, and LUSC when compared to the normal controls." (PMID 38688977, 2024). "The IHC staining of tumor tissues indicated that RAB3B protein is mainly expressed in the cell membrane." (PMID 38688977, 2024). "In this context, we assessed the clinical value of 8 genes (RAB2B, RAB3B, RAB9A, RAB11B, RAB27A, RAB27B, STX1A, and VAMP7), which are implicated in sEVs biogenesis, as well as their association with overall and tumor-derived plasma sEVs levels." (PMID 36980570, 2023). "In vivo tumorigenic studies further confirm the tumor-promoting ability of Rab3B." (PMID 38834947, 2024). "It is suggested that exosomes contain signals for cell-to-cell communication are released into the tumor microenvironment by RAB3B which might be necessary for acquiring the CSLC phenotype." (PMID 35277124, 2022). "From this evidence, it can be inferred that eccDNA, through the amplification of RAB3B, can induce autophagy in tumors, which could consequently enhance tumor cell stemness, leading to drug resistance of cancer cells and affecting the efficacy of tumor therapy." (PMID 39534571, 2023). "By contrast, higher RAB3B methylation occurred in BRCA, CESC, KIRC, KIRP, LUAD, PRAD, and THCA tumor samples." (PMID 38688977, 2024). "DPP7, CDR2L exhibited higher and UNC5C, RAB3B, SLC18A2, GPRASP1, PCDH9 exhibited lower expression in tumor tissues (P<0.05)." (PMID 37384293, 2023). "RAB3B, a member of RAS oncogene family, is shown to be a target of miR-200b, which is supposed to be tumor suppressor in GC." (PMID 32821544, 2020). "In summary, miR-200b low ISH staining was seen in 90% (9/10) tumor samples, while positive rates for RAB21, RAB23, RAB18 and RAB3B IHC staining were 80%, 80%, 90%, 100% respectively." (PMID 24447584, 2014). "Compared with normal breast tissue, miR-200b expression was down-regulated in tumor tissue, while the contrary situations were found for RAB21, RAB23, RAB18 and RAB3B IHC staining." (PMID 24447584, 2014).
tumor (continued). "Interestingly, RAB3A, RAB3B and RAB3D were shown to promote breast, colon, esophagus, melanoma, osteosarcoma and glioma tumor progression by increasing cell proliferation, migration, and invasion." (PMID 38533085, 2024). "Rab3B expression was significantly correlated with lymph node metastasis (P = 0.0014) and tumor stage (P = 0.0058), but not with age, sex, or primary tumor size." (PMID 38834947, 2024). "Our study shows that RAB27A, RAB27B, RAB2B, and RAB3B mRNA levels were lower in tumor tissues compared to tumor adjacent, non-malignant tissues (p < 0.001, p = 0.009, p = 0.011, and p < 0.001, respectively)." (PMID 36980570, 2023). "Interestingly, RAB27A, RAB27B, RAB2B, RAB3B mRNA levels were lower in tumor tissues compared to tumor adjacent, non-malignant tissues (p < 0.001, p = 0.009, p = 0.011 and p < 0.001, respectively)." (PMID 36980570, 2023). "Finally, RAB3B expression is upregulated in aggressive luminal B BC cells in response to the amplification of the inositol-requiring enzyme 1 (IRE-1) gene, which acts as an oncogenic factor to repress a subset of tumor suppressor microRNAs (miRs) via regulated IRE1-dependent decay." (PMID 38533085, 2024).
infection (3 papers, 2018 to 2024). The state of being infected such as from the introduction of a foreign agent such as serum, vaccine, antigenic substance or organism. "EgPSC infection also caused the upregulation of Cgn, Epb41, Cldn8, Shroom3, Cask, Rab3b, Epb41l2, Csnk2b, Prkcb, and MyI12a." (PMID 36713407, 2022).
neurological diseases (1 paper, 2023). "A positive correlation between m1A modification and gene expression was observed, and we selected genes related to neurological diseases (Bag3, Csf1, Cyp1b1, Egfr, Flnc, Lox, Mt1, Nid2, Rab3b, and Tubb4a) for analysis, with MeRIP-RT-PCR and qRT-PCR performed to verify this phenomenon." (PMID 37173310, 2023).
RAB3B also shares sentences with these, for which no sentence is quoted: colorectal cancer (2 papers); hypopharyngeal squamous cell carcinoma (2); adenocarcinoma (1); Adrenocortical carcinoma (1); Astrocytoma (1); Breast invasive carcinoma (1); diabetic kidney disease (1); diffuse large B-cell lymphoma (1); Insulin resistance (1); lung squamous cell carcinoma (1); lymph node metastasis (1); lymphangioleiomyomatosis (1); lymphoid neoplasm (1); major depression (1); mesenchymal tumors (1); myeloid leukemia (1); neurodevelopmental disorder (1); ovarian epithelial tumor (1); pancreatic adenocarcinoma (1); renal fibrosis (1); sarcoma (1); schizophrenia (1); testicular germ cell tumor (1); tuberous sclerosis (1); uterine carcinosarcoma (1).